HIF1A (hypoxia inducible factor 1 subunit alpha)
Diseases named in the same sentence as HIF1A in open-access papers (continued):
Sharing a sentence is not in itself a finding about the gene and the disease.
hepatocellular carcinoma (continued). "The Western blot results indicated that knockdown of miR-210 decreased HIF-1α protein and increased protein expression of MNT, EFNA3 and AIFM3 genes in human hepatoma xenograft." (PMID 23618526, 2013). "In the hepatoma cells, HGF promoted gene expression by increasing HIF activity, and in the HGF-induced survival in carcinoma cells, involved HIF-1α activation." (PMID 23209838, 2012). "This interaction enhances the transcriptional activity of HIF-1α by stabilizing the PLAGL2 protein, thereby forming a MAPKAPK5-AS1/PLAGL2/HIF-1α signaling loop that promotes the malignant phenotype of hepatocellular carcinoma cells, including proliferation, EMT, and metastasis." (PMID 40861273, 2025). "In a study of hepatocellular carcinoma, MAP17 was described as a hypoxia-induced glycolytic regulator in the tumor microenvironment, coupling aerobic glycolysis to tumor growth via the activation of the ROS/AKT pathway and HIF1α." (PMID 40805270, 2025). "In vitro studies revealed that compounds VI and VII both exhibited anti-cancer and anti-angiogenic effects against hepatocellular carcinoma (HCC), primarily by inhibiting hypoxia-inducible factor-1 alpha (HIF-1α) and c-mesenchymal–epithelial transition receptor (c-Met) signaling." (PMID 41195431, 2025). "In hepatocellular carcinomas, it has been demonstrated that HIF-1α is not involved in the regulation of RhoA/ROCK and Rac1/PAK activity." (PMID 38791951, 2024). "In hepatocellular carcinoma cells, SENP1 induces stemness-related genes expression such as Oct3/4, Nanog, NOTCH1 and BMI-1 through enhancing the stability and transcriptional activity of HIF-1α, ultimately leading to cancer cell self-renewal." (PMID 38389923, 2024). "In addition, ginsenoside CK significantly inhibited the binding of Bclaf1 and HIF-1α, thereby suppressing HIF-1α-mediated glycolysis in anoxic human hepatoma cells and inhibiting their proliferation." (PMID 39444606, 2024). "In addition, the hypoxia environment can inactivate the Hippo signaling pathway in hepatoma cells, promote the translocation of YAP and bind to HIF-1α in the nucleus, and maintain the stability of HIF-1α protein to accelerate glycolysis." (PMID 38889502, 2024). "A recent study indicated that CMB9-22P13.1 could upregulate HOTTIP and activate HIF-1α/VEGF signaling, leading to enhanced hepatocellular carcinoma progression and angiogenesis." (PMID 36849926, 2023). "However, overexpression of HIF-1α leads to epithelial–mesenchymal transition (EMT) and metastasis in hepatocellular carcinoma cells." (PMID 37491279, 2023). "HIF-1α, STAT3, and VEGF signaling molecules interact and form the HIF-1α/STAT3/VEGF signal transduction pathway, which probably plays an important role in the occurrence and development of hepatocellular carcinoma." (PMID 37333486, 2023). "In hepatoma cells, kaempferol did not alter the HIF1α protein level but changed its localization by the inactivation of p44/42 MAPK." (PMID 38001865, 2023). "Mechanistically, HIF-1α stimulates LOXL2 expression and tumor progression in hepatoma." (PMID 36906534, 2023). "In accordance with our results, recent evidences have shown that HIF-1α could mediate the expression of TLR4 in pancreatic cancer, oral squamous cell carcinoma, and hepatocellular carcinoma under hypoxia." (PMID 35464826, 2022). "Furthermore, TBN treatment rapidly increased HIF-1α and HIF-2α synthesis both in C57BL/6J mice and hepatoma cells." (PMID 36324690, 2022). "However, further investigation is still needed about the crosstalk between HIF-1α and NF-κB and its effect on EMT in hepatocellular carcinoma cells." (PMID 34073155, 2021). "Additionally, they further demonstrated, in vitro, that such exosomes when delivered to hepatocellular carcinoma (HCC) cells, induce their proliferation, migration, and chemoresistance through the von-Hippel-Lindau (VHL)/HIF-1α axis." (PMID 34283044, 2021).
hepatocellular carcinoma (continued). "Our results depicted attenuation in mRNA and protein expression levels of Hif1- α, VEGF and Akt upon taxifolin treatment in HepG2 and Huh7 cells, suggesting taxifolin can be a viable option for curbing cell survival and angiogenesis in hepatic carcinoma." (PMID 34113483, 2021). "Another two positive feedback loops have been found to coexist in multidrug-resistant hepatocellular cancer cells, HIF-1α/miR-183/IDH2/HIF-1α and HIF-1α/miR-183/SOCS6/p-STAT3/HIF-1α, which may modulate HIF-1α protein." (PMID 33673376, 2021). "In glioblastoma and hepatocellular carcinoma, a hypoxic microenvironment maintains stem cells or promotes reprogramming towards a CSC phenotype, i.e., by inducing EMT via activation of SNAI1 through HIF-1α." (PMID 34771704, 2021). "In human hepatoma cells, AMPK-activated histone deacetylase 5 (HDAC5) deacetylated HSP70, which, in turn, mediated the HSP90-HIF-1α interactions, followed by the nuclear translocation of HIF-1α and induction of the HIF-1-dependent transcription response." (PMID 33806538, 2021). "However, a previous study demonstrated YTHDF2 levels are restored in hypoxic states after siRNA knockdown of HIF1α in both the HEP3B and SMMC7721 hepatocellular carcinoma cell lines." (PMID 33616673, 2021). "Also, PDK1 (a HIF-1α target gene) drives PI3K/AKT/mTOR pathway activation, decreases BAX expression, and renders hepatocellular carcinoma cells resistant to irradiations." (PMID 34539584, 2021). "Apart from the crosstalk between HIF-1α and TGF-β, another important EMT pathway Wnt/β-catenin could also enhance hypoxia-induced EMT by potentiating with HIF-1α signaling in hepatocellular carcinoma." (PMID 32322559, 2020). "In hepatocellular carcinoma, vasodilator-stimulated phosphoprotein (VASP) acts as a tumor premotor and its overexpression at the transcriptional level is mediated by direct binding of HIF-1α to HREs in the VASP promoter region." (PMID 32014012, 2020). "It has been suggested that inhibiting the HIF-1α/PFKFB3/PFK-1 axis with metformin could suppress glycolysis and impair cancer growth in hepatocellular carcinoma, but whether similar effects can be achieved in other cancers is not yet clear." (PMID 33256814, 2020). "In murine liver and hepatoma cells, Hif1a transcript containing exon 1.2 but not exon 1.1 was selectively expressed." (PMID 28493839, 2017). "In this study, we sought to examine the expression of orexin receptors in HepG2 human hepatocellular carcinoma cells, and further investigated whether the orexin A/OX1R-stimulated HIF-1α signaling mediated its effects on glucose metabolism in HepG2 cells." (PMID 28886081, 2017). "Increased expression of HIF-1α and HIF-2α has been reported in many liver diseases, including nonalcoholic fatty liver disease (NAFLD), alcoholic liver disease (ALD), IR-induced liver injury, and hepatocellular carcinoma (HCC)." (PMID 27094811, 2016). "The link between HIF-1α and STAT3 occurs at different levels, and is further supported by studies showing that HIF-1α facilitates the binding of STAT3 to the haptoglobin promoter in HepG2 human hepatoma cells." (PMID 26501341, 2015). "It is also a potent inhibitor of the expression of HIF-1α and VEGF and may represent a new promising therapeutic approach in the treatment of hepatocellular carcinoma." (PMID 26003166, 2015). "Collectively, these findings suggested that metformin may target the AMPK/mTOR/HIF-1α/P-gp and MRP1 pathways to reverse MDR in hepatocellular carcinoma." (PMID 25310259, 2014). "The most relevant studies in comparison to our work are the identification of S1P as a non-hypoxic regulator of HIF-1α expression in vascular endothelial and smooth muscle cells and in HepG2 liver carcinoma cells." (PMID 23824493, 2013). "Treating HepG2 cells with desferrioxamine, an iron chelator that stabilizes HIF-1α, increased hepatoma migration threefold, demonstrating a role for HIF-1α in hepatoma migration independent of HCV infection." (PMID 22178269, 2012).
hepatocellular carcinoma (continued). "Treating hepatoma cells with an independent HIF-1α inhibitor, RITA, confirmed these findings (data not shown)." (PMID 22178269, 2012). "MSC when administered alongside irinotecan chemotherapy improved clinical outcome in mice with human squamous cell tumour xenografts through inhibition of HIF-1α and NAC was shown to reduce HIF activity in mouse models of hepatocellular carcinoma and B cell lymphoma." (PMID 22414300, 2011). "While HIF-1α-deficient fibrosarcoma cells (HT1080) displayed significantly enhanced sensitivity towards etoposide under ambient air, colon cancer (HCT116) and hepatoma (Hepa-1) cells failed to do so." (PMID 20706634, 2010). "For instance, in hepatocellular carcinoma (HCC), the increase in intracellular copper levels induced by ionizing radiation promotes the transcriptional activity of Hypoxia Inducible Factor 1 Subunit Alpha (HIF1A), thereby elevating the expression levels of ceruloplasmin and SLC7A11 within cells." (PMID 40200790, 2025). "For instance, HIF-1α has been shown to directly stimulate the transcription of YTHDF1, thereby facilitating hepatocellular carcinoma (HCC) autophagy and malignancy by enhancing the translation of ATG2A and ATG14." (PMID 40136363, 2025). "By binding with HIF1α, FASN promotes HIF1α nuclear translocation, inhibits HIF1α ubiquitination and proteasome degradation, and then enhances the transcription of carrier family 7 member 11 (SLC7A11), enhancing the iron death resistance of hepatocellular carcinoma cells induced by sorafenib." (PMID 41421797, 2025). "In a separate assay involving hepatocellular carcinoma, the potential for cell migration and invasion was evaluated using Transwell assays, revealing that the knockdown of lncRNA MIAT or the absence of HIF-1α inhibited the proliferation, migration, and invasion of hypoxia-treated hepatoma cells." (PMID 40861273, 2025). "In hepatocellular carcinoma (HCC), EFNA3, promoted by HIF1-α under hypoxia conditions, affected the self-renew, proliferation and migration of HCC cells." (PMID 38630320, 2024). "In hepatocellular carcinoma cells (HCC), CA curbed VEGF and vascularization induced by CoCl2, accomplishing this through the stabilization of STAT3/JNK1/HIF-1α." (PMID 39062873, 2024). "The HIF-1α, VEGF and VEGFR signaling pathways may also be involved in the formation of new blood vessels in the peripheral infiltration area of HAE, which has similar biological characteristics to those of hepatocellular carcinoma." (PMID 39619441, 2024). "In hepatocellular carcinoma (HCC), hypoxia-inducible factor-1α (HIF-1α) can promote VM formation through LOXL2 upregulation and eventually lead to the metastasis and progression of HCC." (PMID 38459564, 2024). "Excessive activation of RAS/MAPK signaling is commonly observed in hepatocellular carcinoma (HCC), and it has been found that RIT1 induces angiogenesis through the MEK/ERK/EIF4E/HIF1-α/VEGFA axis." (PMID 36941564, 2023). "In human hepatocellular carcinoma (HCC), entonucleoside triphosphate diphosphohydrolase 2 (ENTPD2), a direct transcriptional target of HIF-1α, is predominantly upregulated in hypoxia." (PMID 37460927, 2023). "In hepatocellular carcinoma, CAF-derived CCL5 (also known as RANTES) promotes metastasis by binding to a specific receptor, CCR5, and inhibiting the ubiquitination and degradation of HIF-1α, maintaining HIF-1α even under normoxia, thereby upregulating the downstream gene ZEB1 and inducing EMT." (PMID 36831453, 2023).
hepatocellular carcinoma (continued). "Particularly, PARP14 can promote glycolysis in different tumor models, such as human hepatocellular carcinoma (HCC), by maintaining reduced PKM2 activity; on the other hand, a close relationship between c-myc and AKT has been reported in B lymphomas and AML through the NF-κB/HIF-1α axis." (PMID 37520325, 2023). "HIF-1α could directly bind to the promoter of MAPKAPK5-AS1 to activate gene transcription, and ectopic expression of lncRNA MAPKAPK5-AS1 under hypoxia could promote hepatocellular carcinoma growth, metastasis and EMT." (PMID 35819532, 2022). "Additionally, there have been a few studies on SIRT3/HIF-1α pathway in cervical cancer and hepatocellular cancer but not in DTC." (PMID 35136826, 2022). "Under hypoxic conditions, irradiated hepatoma carcinoma HepG2 or glioblastoma T98G cells can promote the expression of HIF-1α, which would result in radioresistance, but the conditioned medium from these cells can inhibit HIF-1α expression and induce cell damage in bystander cells." (PMID 33869184, 2021). "SENP1 regulates hepatocellular carcinoma (HCC) carcinogenesis through deSUMOylation of ubiquitin-conjugating enzyme E2T (UBE2T) and HIF1α." (PMID 34503213, 2021). "PSMD4 increases cell proliferation via regulation of the PTEN/Akt pathways in hepatocellular carcinoma (HCC) cells; in addition, a significant correlation has been found between HIF1a expression and PSMD4 expression in HCC patients." (PMID 33110365, 2020). "In hepatocellular carcinoma cells, overexpressed lncRNA UBE2CP3 enhances human umbilical vein endothelial cell proliferation, migration and angiogenesis, which is attributed to the ERK/p70S6K/HIF-1α/VEGFA signaling axis activated by lncRNA expression deviating from normal status." (PMID 32014012, 2020). "Interestingly, another study indicated that cZNF292 was induced by hypoxia in a time-dependent manner in hepatoma cells independent of HIF1α, promoting hypoxic hepatoma proliferation, VM, and radioresistance." (PMID 31973726, 2020). "The expression level of HIF-1α in tissues of TFAE treated groups remarkably decreased compared with mice in negative control group, indicating that TFAE inhibited HIF-1α expression level in hepatoma cells, leading to the decreased ability to tolerate hypoxia and proliferation." (PMID 29348766, 2017). "One study reported that sorafenib, a multikinase inhibitor, switches from HIF-1α- to HIF-2α-dependent pathways, resulting in resistance to sorafenib in hypoxic hepatocellular carcinoma (HCC) by activating the TGF-α/EGFR pathway." (PMID 28476028, 2017). "We analyzed correlation between HIF-1α and CXCL8 levels, tumor characteristics and overall survival in 102 hepatocellular carcinoma (HCC) patients." (PMID 26078356, 2015). "Moreover, Ser727-phosphorylated STAT3 was effectively inhibited in HSC-CM-treated hepatoma cells by the IL-8 neutralizing antibody, whereas HIF-1α and NF-κB p65 activation was not affected." (PMID 26593962, 2015). "In each of two cell lines studied, Hep3B (derived from human hepatoma cells) and HEK293T (derived from human embryonic kidney cells), substantially more PTPRZ1 promoter activity, as assessed using a luciferase reporter assay, was observed in response to HIF-2α as compared to HIF-1α." (PMID 20224786, 2010). "The hypoxic environment in hepatocellular carcinoma (HCC) contributes to angiogenesis, invasiveness, and chemoresistance by upregulating the expression of vascular endothelial growth factor (VEGF) and hypoxia-inducible factor 1α (HIF-1α)." (PMID 37576900, 2023).
hepatocellular carcinoma (continued). "An anti-HIF-1α oligonucleotide EZN-2968 had been tested in advanced solid tumors, lymphoma, and hepatocellular carcinoma (HCC) in different Phase I trials (US National Library of Medicine, 2011; US National Library of Medicine, 2018a; US National Library of Medicine, 2018b)." (PMID 36846589, 2023). "To investigate the interaction between BMP9 and angiogenic factors in HCC, we first explored the gene expression correlation between BMP9 (GDF2) and the angiogenic proteins VEGFR2 (KDR) and HIF-1α (HIF1A) in The Cancer Genome Atlas Liver Hepatocellular Carcinoma (TCGA-LIHC) cohort." (PMID 35163396, 2022). "Specifically, HIF-1α was found to be a direct transcriptional target of NPAS2, which mediates both the upregulation of glycolytic genes and the downregulation of mitochondrial biogenesis in hepatocellular carcinoma (HCC)." (PMID 33042011, 2020). "Hence, inhibition of HIF-1α and STAT3 could prove valuable for therapy of hepatocellular carcinoma." (PMID 18651980, 2008). "NRF2 knockdown significantly decreased the nucleus accumulation of HIF-1α without changing its mRNA expression, while HIF-1α silencing did not affect NRF2 protein expression in HepG2 human hepatoma cells." (PMID 37946175, 2023). "For example, in hepatocellular carcinoma (HCC) tumor tissue, c-Myc expression showed a positive correlation with HIF2α but not with HIF1α." (PMID 37361539, 2023). "In a study of m6A methylation in hepatocellular carcinoma, hypoxic states were concomitant with reduced YTHDF2 levels, and this effect was predominantly exerted by HIF2α repression rather than HIF1α." (PMID 33616673, 2021). "In a model of hepatocellular carcinoma (HCC), HIF-1α upregulated the expression of chemokine (C-C motif) ligand 26 (CCL-26) in cancer cells, recruiting chemokine (C-X3-C motif) receptor 1 (CX3CR1) expressing-MDSCs to primary tumours and promoting HCC tumour growth." (PMID 31835751, 2019). "It has not been addressed if HIF-1α-mediated downregulation of PGC-1β also affects mitochondrial biogenesis and mass in hepatoma cells." (PMID 26258123, 2015). "In some other conditions, VEGF expression and angiogenesis were independent of HIF-1α level, e.g. under hypoxic conditions,VEGF expression in hepatocellular carcinoma cells was HIF-1-independent, but was primarily controlled by the Akt/PI3K and SP1 pathways." (PMID 25823960, 2015). "Similarly, no stabilization of HIF-1α was observed in cultured human embryonic kidney (HEK293), hepatocellular carcinoma (Hep3B) and neuroblastoma (Kelly) cells and fibroblasts upon treatment with succinate diethyl or dimethyl ester." (PMID 39765906, 2024). "GSTZ1 could decrease the protein but not mRNA level of HIF-1α under hypoxia in hepatoma cells, indicating that GSTZ1 may negatively modulate HIF-1α expression at the protein level." (PMID 37906252, 2023). "For example, treatment with the TX-402 inhibitor of HIF-1α expression downregulates the transcription of HIF-1α target genes GLUT-1 and erythropoietin but not MMP-7, MMP-14, or Ets-1 when hepatocellular carcinoma HepG2 and Hep3B were cultured in hypoxic conditions (1% oxygen)." (PMID 38069210, 2023). "In hepatoma cells, HIF-1α induced MCL-1 upregulation is anti-apoptotic while in small cell lung cancer cell lines, hypoxia induced MCL-1 downregulation is independent of HIF-1α." (PMID 28404924, 2017). "Therefore, the levels of HIF1α in four other cell lines including PC-12 (rat neural cell), HT1080 (human fibrosarcoma cell), GES-1 (human gastric epithelial cell), and SK-Hep-1 (human hepatoma cell) were monitored with or without myriocin treatment." (PMID 35784791, 2022).
hepatocellular carcinoma (continued). "Our results show that in hepatocellular carcinoma (HCC) cell lines, hypoxia did not alter SIRT1 mRNA or protein expression, whereas it predictably led to the accumulation of HIF-1α and the up-regulation of its target genes." (PMID 22479397, 2012).